UCA1 (urothelial cancer associated 1)
Diseases named in the same sentence as UCA1 in open-access papers (continued):
Sharing a sentence is not in itself a finding about the gene and the disease.
bladder cancer (continued). "The role of UCA1 in cell apoptosis was also found in several types of cancers such as bladder cancer, breast cancer, gastric cancer and others." (PMID 31596734, 2019). "UCA1 was a novel lncRNA which was first discovered in 2006 in human bladder cancer and has become a hot spot in recent years." (PMID 30918102, 2019). "The mutual inhibitory effect and the inverse expression of UCA1 and hsa-miR-1 have already been proven in bladder cancer and one functional interaction site was experimentally confirmed between hsa-miR-1 and UCA1." (PMID 31694571, 2019). "LncRNA UCA1 has been reported to induce drug resistance in bladder cancer and many other cancers, thereby greatly reducing the efficacy of cancer therapy." (PMID 31293964, 2019). "Similar to MALAT1, UCA1 was also reported to induce increase of the migratory and invasive abilities of bladder cancer cells by inducing EMT." (PMID 30813594, 2019). "Accumulating evidence revealed that UCA1 was dysregulated in cancer tissues and participated in the malignant progression of cancers, including bladder cancer, breast cancer, gastric cancer (GC), colorectal cancer (CRC) and lung cancer." (PMID 30918102, 2019). "For instance, lncRNA UCA1 functions as a ceRNA to enhance mitochondrial function and cell viability in bladder cancer by sponging miR-195 to up-regulate ARL2 expression." (PMID 31531526, 2019). "Ectopic expression of lncRNA UCA1 in bladder cancer cell line BLS-211 demonstrated that UCA1 was oncogenic." (PMID 31133028, 2019). "Metformin inhibited proliferation and glycolysis in bladder cancer cells through regulation of long non-coding RNA UCA1." (PMID 30853913, 2019). "UCA1 was firstly identified to be over-expressed in bladder cancer and was considered to function as a biomarker for the bladder cancer diagnosis." (PMID 31480503, 2019). "UCA1 exhibits high sensitivity, strong specificity, and stable experimental results with respect to bladder cancer." (PMID 30940184, 2019). "UCA1 is reported to be overexpressed in bladder cancer and it promotes bladder cancer cell proliferation, migration, and invasion." (PMID 29642505, 2018). "The promoting effect of BMP9 on bladder cancer cells was rescued after interfering with UCA1 in BMP9 overexpressed bladder cancer cells both in vitro and in vivo." (PMID 29642505, 2018). "UCA1 was originally reported to be over-expressed in bladder cancer and was suggested to be a biomarker for the diagnosis of bladder tumors." (PMID 29669595, 2018). "BMP9 has an ambiguous role in tumor progression, but it was recently shown that BMP9 stimulated UCA1 expression in bladder cancer cells." (PMID 30441811, 2018). "The expression of H19, SNHG16 and UCA1 was significantly elevated in bladder cancer tissues, while PTENP1 and MEG3 were significantly decreased in bladder cancer tissues compared with adjacent normal tissues (P < 0.05)." (PMID 30285771, 2018). "The expression of SNHG16, MALAT1, and UCA1 were up-regulated in bladder cancer tissue, while the expression of YRNA1, YRNA3, YRNA4, YRNA5, and MEG3 were down-regulated." (PMID 29899709, 2018). "The lncRNA UCA1 is upregulated in bladder cancer and induces EMT, migration, and invasion of bladder cancer cells." (PMID 29618386, 2018). "UCA1 is a recently identified long non-coding RNA and characterized as a sensitive and specific marker for human bladder cancer." (PMID 29642505, 2018). "As a result, the overall pooled sensitivity and specificity of UCA1 for bladder cancer were 0.84 and 0.89, respectively, along with an AUC value of 0.92, suggesting that the diagnostic accuracy of UCA1 was moderate." (PMID 29899709, 2018). "In bladder carcinoma, lncRNA UCA1 is overexpressed and promotes glycolysis by upregulating hexokinase 2 (HK2), which promotes aerobic glycolysis and acts as the key indicator of the Warburg effect." (PMID 30134946, 2018).
bladder cancer (continued). "For example, UCA1 has three isoforms, but only the 1.4 kb (v1) isoform promotes bladder cancer proliferation and metastasis." (PMID 29535820, 2018). "Mechanistically, UCA1 regulates bladder cancer cell migration and invasion by miR-145 and its target genes actin-bundling protein fascin and zinc finger E-box binding homeobox 1 and 2 (ZEB1/2)." (PMID 29618386, 2018). "The oncogenic functions of UCA1 have been studied extensively in various cancer types, including bladder cancer, acute myeloid leukemia, breast cancer, colorectal cancer, etc30." (PMID 30349036, 2018). "The pooled DOR of 27.01 (95% CI, 8.69-83.97) suggested that the overall accuracy of UCA1 for the diagnosis of bladder cancer is credible." (PMID 28415640, 2017). "To investigate the functional roles of UCA1 in bladder cancer, we observed the changes of cell phenotypes caused by UCA1 downregulation via CRISPR/Cas 9-UCA1-1 or UCA1-8 transfection." (PMID 28038452, 2017). "Single CRISPR/Cas9-UCA1 can effectively inhibit UCA1 expression when transfected into 5637 and T24 bladder cancer cells, while the combined transfection of the two most effective CRISPR/Cas9-UCA1s can generate more satisfied inhibitory effect." (PMID 28038452, 2017). "A recent study reported that knockdown of miR-1 resulted in Ago2-slicer-dependent lncRNA UCA1 overexpression, whereas miR-1 overexpression decreased UCA1 levels in bladder cancer cells." (PMID 28969100, 2017). "LncRNA UCA1 functions as an oncofetal gene similar to lncRNA H19 and is detected not only in tumor tissue samples but also in blood and urine samples from bladder cancer patients as a circulating biomarker." (PMID 28969100, 2017). "To investigate the functions of lncRNA UCA1 in bladder cancer, we designed eight gRNAs targeting the promoter or the exon of UCA1, and we obtained two gRNAs with highly suppressive activity for this research." (PMID 28038452, 2017). "UCA1, first cloned from bladder cancer cells and shown to play an important regulatory role in malignancies in the urinary system, was identified as a key factor in the effect of ART on PCa cell lines." (PMID 28209917, 2017). "LncRNA UCA1 is the most abundant isoform in various malignant tumors such as bladder cancer, breast cancer and hepatocellular carcinoma." (PMID 28969100, 2017). "The lncRNA UCA1 was firstly discovered to be up-expressed in the carcinogenesis of bladder cancer in 2006." (PMID 28380443, 2017). "UCA1 is located on chromosome 19p13.12 and was reported to be highly expressed in bladder cancer cells and to be involved in promoting migration and invasion during tumorigenesis." (PMID 29212166, 2017). "For instance, UCA1 was reported to play a regulatory role in promoting human bladder cancer proliferation." (PMID 28389669, 2017). "Blood UCA1 levels were elevated in patients with advanced bladder cancer after cisplatin-based combination chemotherapy." (PMID 28410618, 2017). "We have characterized the lncRNA UCA1 from human bladder cancer cell line BLZ-211 as an oncofetal gene." (PMID 28038452, 2017). "In bladder cancer, UCA1 and miR-1 expressions were inversely correlated, and overexpression of miR-1 phenocopied the knockdown of UCA1." (PMID 28715488, 2017). "UCA1 was found to be upregulated in tongue squamous cell carcinomas, gastric cancer, breast cancer and bladder cancer." (PMID 29207643, 2017). "Silencing of UCA1 decreased ROS production and promoted mitochondrial glutaminolysis in bladder cancer cells." (PMID 29147648, 2017). "Taken together, circulating UCA1 is a promising biomarker for bladder cancer diagnosis and therapeutic monitoring." (PMID 28410618, 2017). "UCA1 was originally identified as being overexpressed in bladder cancer and it functions as an oncogenic lncRNA in a variety of different tumor types." (PMID 27902466, 2017).
bladder cancer (continued). "For example, lncRNA H19 promoted colorectal cancer progression by epigenetically repressing miR-200a, and LncRNA UCA1 contributed to tumor growth by down-regulating miR-16 in bladder cancer." (PMID 29212233, 2017). "Previous studies showed that UCA1 promoted gemcitabine/cisplatin resistance by CREB regulating miR-196a-5p expression in the bladder cancer cells." (PMID 29207643, 2017). "In bladder cancer, the up-regulation of UCA1 was found to induce EMT, tumor cell migration and invasion and it was shown to contribute to cisplatin and gemcitabine resistance." (PMID 28415801, 2017). "Human UCA1 was first identified in human bladder carcinoma, and also reported in other human cancers." (PMID 27893417, 2017). "UCA1 abundance is correlated with clinico-pathological parameters (particularly in bladder cancer), suggesting higher abundance as a marker of higher histologic grade." (PMID 27902466, 2017). "In the present study, we verify the utility of CRISPR/Cas9 system in mechanistically studying lncRNAs by deleting UCA1, and verify UCA1 as an onco-lncRNA promoting bladder cancer progression." (PMID 28038452, 2017). "Higher lncRNA UCA1 levels were observed in blood samples of advanced bladder cancer patients after cisplatin-based chemotherapy with a positive correlation between UCA1 and Wnt6 mRNA expression levels in the bladder cancer tissues." (PMID 28969100, 2017). "Transcription factors Ets-2 and C/EBPα upregulate lncRNA expression in bladder cancer cells by directly binding to the core promoters and enhancing UCA1 promoter activity." (PMID 28969100, 2017). "In our previous study, we found that UCA1 was expressed in both 5637 and T24 bladder cancer cell lines, and UCA1 level in 5637 cells was higher than that in T24 cells." (PMID 28038452, 2017). "Despite these limitations, the present evidence suggests that urine UCA1 is potential to be a diagnosis biomarker for bladder cancer, due to this non-invasive method has good overall diagnostic performance." (PMID 28415640, 2017). "In bladder carcinoma cells, UCA1 regulates cell cycle progression through CREB and via PI3K-AKT-dependent signalling pathways." (PMID 27902466, 2017). "Similar studies of UCA1 have also been reported in other cancers involving the knockdown of UCA1, and resulting in the inhibition of bladder cancer proliferation in vivo." (PMID 29212166, 2017). "Actually, the function of UCA1 in bladder cancer cells were consistent that it promoted cell cycle progression, apoptosis inhibition, and MMPs enhancement." (PMID 28038452, 2017). "Ectopic expression of lncRNA UCA1 in bladder cancer cell line BLS-211 promoted cancer progression demonstrating that lncRNA UCA1 was oncogenic." (PMID 28969100, 2017). "In bladder cancer expression of this lncRNA is elevated following cisplatin treatment and knockdown of UCA1 re-sensitizes bladder cancer cells to cisplatin." (PMID 28430163, 2017). "UCA1 was firstly characterized as an effective diagnosis biomarker in bladder cancer with a high sensitivity and specificity (80.9% and 91.8%)." (PMID 28423704, 2017). "The binding of miR-1 to UCA1 has been confirmed by luciferase reporter assay in bladder cancer and, accordingly, in vitro upregulation of miR-1 induced UCA1 downregulation and caused a decreased cell growth and migration and also an augmented apoptosis." (PMID 29147648, 2017). "Fan reported that UCA1 plays an important role in the chemoresistance of bladder cancer by activating Wnt signaling in a Wnt6-dependent manner." (PMID 28209917, 2017). "Hif-1α specifically binds two HREs in the UCA1 lncRNA promoter, leading to its activation in hypoxic bladder cancer cells." (PMID 28327666, 2017). "Researches also indicated that UCA1 enhanced CDDP resistance in ovarian cancer 19 and bladder cancer 20, and increased 5‐fluorouracil resistance in colorectal cancer 11, indicating the critical role of UCA1 in chemoresistance." (PMID 29125238, 2017).
bladder cancer (continued). "RT-PCR based lncRNA UCA1 expression detection in urine samples is an effective and noninvasive assay with high sensitivity (100%) and specificity (67%) for the diagnosis of bladder cancer with the standard cytology method." (PMID 28969100, 2017). "UCA1 is a well-characterized lncRNA that was initially identified in urinary bladder cancer tissues, where it was found to significantly enhance bladder cancer cells’ tumorigenicity and invasive potential in vitro and in vivo." (PMID 28327194, 2017). "UCA1 has been found to be highly expressed in bladder cancer tissues compared to adjacent normal tissues." (PMID 27189224, 2016). "In consistent with the effect of lncRNA UCA1 in bladder cancer, we demonstrated in the current study that the expression of lncRNA UCA1 was elevated in late stages of breast cancer and positively correlates with the mortality of patients." (PMID 27977766, 2016). "Increasing evidences have shown that UCA1 is dysregulated in other cancers, such as bladder carcinoma, colorectal, melanoma, breast, gastric, and esophageal squamous cell carcinoma." (PMID 27977766, 2016). "It was found that miR-1 decreased the expression of UCA1 in bladder cancer cells in an Ago2-slicer-dependent manner." (PMID 26949706, 2016). "Taken together, these limited clinical data indicate that circulating UCA1 is a promising biomarker for bladder cancer diagnosis and therapeutic monitoring." (PMID 27189224, 2016). "In bladder cancer, the lncRNA UCA1 participates in ROS formation and promotes mitochondrial glutaminolysis by its sponge effect on miR-16." (PMID 27551267, 2016). "As to UCA1, several reports have revealed its potential in different types of cancer, including breast cancer, ovarian cancer as well as bladder cancer." (PMID 27863388, 2016). "In human bladder cancer cells, the expression of a long non-coding RNA UCA1 promoted glycolysis via a 0.5-fold increase in hexokinase 2 expression." (PMID 26887408, 2016). "The UCA1 test cannot replace cystoscopy for the evaluation of patients with suspected primary BC or in the context of a follow-up for bladder cancer." (PMID 26191476, 2015). "The efficiency of the UCA1 test for the detection of primary and recurring bladder cancer in our study was lower than previously reported." (PMID 26191476, 2015). "It has been presented that UCA1 functions in regulation of embryonic development and in bladder cancer invasion and progression, as well as breast tumor and colorectal cancer." (PMID 26136615, 2015). "UCA1 was first identified in bladder cancer cells and is involved in bladder cancer invasion and progression." (PMID 26160838, 2015). "UCA1 has also been found to enhance bladder cancer cell proliferation and metastasis by disrupting the PI3K/Wnt signaling pathway." (PMID 26378581, 2015). "A pilot study took advantage of this to evaluate potential application of UCA1 in urinary sediments from patients with bladder carcinomas." (PMID 26448935, 2015). "We confirmed the role of UCA1 as a possible adjunct to cystoscopy and cytology when a primary bladder cancer is suspected, but its role in the follow-up of recurring tumours remains limited." (PMID 26191476, 2015). "It has been previously shown that the UCA1 promoter contains C/EBPα binding sites and that the C/EBPα protein can bind to the UCA1 promoter region both in vitro and in vivo in bladder cancer cells." (PMID 26053097, 2015). "In the present study, we first examined the function of UCA1 in 5637 bladder cancer cells, which express high levels of UCA1." (PMID 24993775, 2014). "For this reason, we investigated BRG1 and UCA1 expression in tissue specimens of 20 bladder cancer patients with real-time PCR." (PMID 24993775, 2014). "UCA1 is expressed in bladder transitional cell carcinomas and influences tumorigenic potential of bladder cancer cell lines." (PMID 24876127, 2014).
bladder cancer (continued). "We found that UCA1 plays an oncogene-like role in this bladder cancer cell line, which is consistent with previous reports." (PMID 24993775, 2014). "To explore the significance of the association of UCA1 with BRG1, we first investigated BRG1 function in bladder cancer." (PMID 24993775, 2014). "Previous studies reported that UCA1 seems to function as a tumor-promoting factor in bladder cancers." (PMID 24993775, 2014). "Collectively, these results demonstrate that UCA1 promotes bladder cancer cell proliferation by inhibiting BRG1." (PMID 24993775, 2014). "To investigate the function of UCA1 lncRNA in urinary bladder cancer, we used the 5637 urinary bladder cell line that highly expresses UCA1." (PMID 24993775, 2014). "A pilot study took advantage of this to evaluate the potential application of UCA1 in urinary sediments from patients with bladder cancer." (PMID 24006935, 2013). "A previous study in our laboratory also implied that elevated UCA1 expression can influence bladder cancer cell growth and promote invasion of the bladder cancer cells, suggesting it would be a novel therapeutic target gene of bladder cancer." (PMID 24069250, 2013). "Despite this interest, little is known about the cis-regulatory elements directly involved in the transcriptional modulation of the UCA1 gene in bladder cancer." (PMID 24069250, 2013). "In bladder cancer, lncRNA UCA1 upregulates CREB activity through enhancing AKT activity, while blocking PI3-K pathway by PI3 Kinase inhibitor can downregulate lncRNA UCA1 expression and reduce cell cycle progression." (PMID 23725405, 2013). "When BLZ-211 cells, expressing UCA1, were inoculated into nude mice, their capacity for tumor formation was increased and strongly suggested that UCA1 has oncogenic function in bladder cancer development." (PMID 24006935, 2013). "UCA1 lncRNA was first found in bladder cancer and located at chromosome 19p13.12." (PMID 40568293, 2025). "Furthermore, the long non-coding RNA (lncRNA) UCA1 facilitates bladder cancer progression by recruiting the transcription factor TWIST1 to the promoter regions of IMPDH1 and IMPDH2, thereby upregulating their expression." (PMID 41179679, 2025). "Recently, a technique was used to inhibit the urothelial cancer-associated 1 (UCA1) long non-protein-coding RNA by CRISPR/Cas9 to prove that the target has a role in the progression of bladder cancer." (PMID 38534656, 2024). "Both single-exosomal UCA1 and single-exosomal MALAT1 exhibited relatively satisfactory diagnostic accuracy with an AUC of 0.77 and 0.79, respectively, manifesting their potential as noninvasive diagnostic biomarkers for bladder cancer." (PMID 38227115, 2024). "Other lncRNAs are under study as potential biomarkers for diagnosis of other cancers, such as lncRNA LINC00152 for hepatocellular carcinoma, lncRNA H19 for gastric cancer, lncRNA UCA1 for bladder cancer and oral squamous cell carcinoma, MEG 3 for multiple myeloma, etc.." (PMID 37143733, 2023). "LncRNA UCA1 improved mitochondrial function for bladder cancer cells and may operate as a probable target for diagnosis and treatment." (PMID 36890266, 2023). "Additionally, UCA1 interacts with miR-196a-5p for bladder cancer through boosting cancer cell invasion by targeting Fascin homologs." (PMID 37245177, 2023). "The lncRNA UCA1 increased Wnt6 expression and cisplatin resistance in bladder cancer cells." (PMID 37405480, 2023). "However, there is still little information on how UCA1 affects guanine nucleotide metabolism in bladder cancer." (PMID 37215997, 2023). "In order to determine whether UCA1 plays a role in purine synthesis in bladder cancer, we analyzed the enzymes involved in the purine synthesis pathway (including guanine nucleotide synthesis and adenine nucleotide synthesis)." (PMID 37215997, 2023).